INSR (insulin receptor)
Diseases named in the same sentence as INSR in open-access papers (continued):
Sharing a sentence is not in itself a finding about the gene and the disease.
non-alcoholic fatty liver (1 paper, 2014). A benign form of fatty non-alcoholic fatty liver disease where the disease has not yet progressed to the inflammation of liver. "In addition, inflammatory cytokines can cause insulin receptor signal transduction abnormalities, leading to the dysfunction of pancreatic β cells, participation in macrovascular and microvascular complications, and leading to retinopathy, non-alcoholic fatty liver and other serious consequences." (PMID 24633252, 2014).
ovarian dysfunction (1 paper, 2022). The inability of the ovaries to function. "Similar to our study, female mice with CNS-specific KO of insulin receptor exhibited ovarian dysfunction and reduced serum and RNA levels of LH." (PMID 35464428, 2022).
overgrowth syndrome (1 paper, 2023). A group of syndromes caused by genetic birth defects that may lead to the development of malignancies. "We propose that variants in the post insulin receptor signalling cascade should be considered in the differential diagnosis of congenital hypoglycaemic disorders even if typical features suggestive of mosaic overgrowth syndromes are absent." (PMID 37974153, 2023).
pancreatic neuroendocrine cancer (1 paper, 2020). "In a pancreatic neuroendocrine cancer model, InsR knockout tumors are suppressed by anti-IGF-IR therapy, whereas InsR-expressed tumors are resistant to this therapy." (PMID 32493414, 2020).
parasite infection (1 paper, 2025). "During parasite infection, the insulin receptor (IR) of parasitic nematodes regulates development and metabolism through activation by insulin-related peptides." (PMID 41406115, 2025).
pheochromocytoma (1 paper, 2014). "NICTH has also been reported in conjunction with paraneoplastic production of insulin receptor antibodies, tumor necrosis factor (TNF), interleukin (IL) -1 and -6, catecholamine (pheochromocytoma) and IGF-1." (PMID 24934576, 2014).
prion disease (1 paper, 2017). A transmissible disease that is caused by a protein that is able to induce abnormal folding of normal cellular proteins, leading to characteristic spongiform brain changes, which are associated with neuronal loss without an inflammatory response. "Worthy of note, three KEGG pathways were more recurrent: prion diseases, TGF-beta signaling, insulin receptor signaling; such bioinformatics data reinforce the link between AMD and AD." (PMID 28424619, 2017).
progeria (1 paper, 2023). "Human senescent and mouse progeria myoblasts showed diminished levels of the insulin receptor, and significantly decreased glucose uptake, and insulin resistance, yet SM cells produced higher levels of energy." (PMID 36797255, 2023).
prostate adenocarcinoma (1 paper, 2002). "But PA-III rat prostate adenocarcinoma cells have no insulin receptor, though they do have specific binding sites for IGF-I and II." (PMID 12232754, 2002).
psychosis (1 paper, 2025). "Our results indicate that INSR and NFXL1 variants may have a role in psychosis that requires to be investigated further." (PMID 40430072, 2025). "Our research indicates a need for further evaluation of INSR, NFXL1 and possibly RYR1 in psychosis in humans." (PMID 40430072, 2025).
renal clear cell carcinoma (1 paper, 2022). "For example, INSR was downregulated in late stage of renal clear cell carcinoma, which was negatively correlated with worse prognosis of patients." (PMID 35513851, 2022).
Retinal dystrophy (1 paper, 2022). Retinal dystrophy is an abnormality of the retina associated with a hereditary process. "Next, we sought to characterize the pattern of INSR expression associated with retinal dystrophy." (PMID 35444190, 2022).
schizoaffective disorder (1 paper, 2025). "INSR SNPs rs2229431 and rs12610022 were found to be significantly different in allele frequencies and genotypic distributions in schizoaffective disorder patients as compared to the controls." (PMID 40430072, 2025).
skin cancer (1 paper, 2024). "Fourth, owing to the lack of reliable genetic tools, we were unable to evaluate the effects of certain antidiabetic drug target perturbations (such as INSR and DPP4) on skin cancer." (PMID 39640975, 2024).
thyroid tumor (1 paper, 2022). A benign or malignant neoplasm affecting the thyroid gland. "Insulin receptor (IR) overexpression has been demonstrated as a factor promoting the proliferation and survival of breast, lung, colonic ovarian, endometrial and thyroid tumors." (PMID 36230790, 2022).
Turner syndrome (1 paper, 2017). Turner syndrome is a chromosomal disorder associated with the complete or partial absence of an X chromosome. "Eight TFs and four ERFs are among the differentially expressed genes, as well as eight genes associated with Turner syndrome (PROCR, NR3C1, INSR, APOB, BMP15, F8, IL6, and WAS) and two genes that are haploinsufficient in humans (RAD50 and SLC33A1)." (PMID 28818098, 2017).
cancer (352 papers, 2006 to 2026). A tumor composed of atypical neoplastic, often pleomorphic cells that invade other tissues. "For the PPTP/C models, higher INSR expression was associated with reduced activity of cixutumumab, consistent with results for adult cancer models showing that signaling through both IR-A and IR-B can mediate resistance to antibodies blocking IGF1R signaling." (PMID 39510293, 2024). "The insulin receptor in acinar cells is causal in supporting cancer initiation in diet-induced Obesity." (PMID 38831236, 2024). "In fact, in the context of the IGF system, this affects both the quantification of cancer-specific IGF-II (o-glycosylated IGF-II pro-hormone) as well as the insulin receptor fetal isoform variant (IRA) in patient-derived cancer cells." (PMID 38255147, 2023). "We identified that TCF7L2 rs290481, INS rs689, and INSR rs1799817 SNPs increased the susceptibility of AEG in different cancer stage subgroups." (PMID 31211453, 2019). "INSR, upregulated 3.15-fold (q = 0,027) in the outliers, was reported to be overexpressed in several cancer types and was associated with poor prognosis when overexpressed on tumor-associated blood vessels in MIBC." (PMID 30419021, 2018). "In NASH-HCCs, the 16 mutated genes involved in insulin signaling included insulin receptor (Insr) and some other well-known cancer-related genes (Mtor, Hras1, Akt3, etc), with Mtor and Hras1 recurrently mutated." (PMID 30367044, 2018). "PI3K is a phosphatidylinositol kinase existing in many kinds of cancer cells and can be activated by a range of cytokine receptors including insulin receptor, growth factor receptor, proto oncogene encoding, and G protein-coupled receptor." (PMID 29358963, 2017). "A growing number of studies have implicated the insulin receptor pathway in cancer development and progression." (PMID 27537218, 2016). "The insulin receptor activating signaling pathways are also associated with invasion and metastasis of malignant tumors." (PMID 26779376, 2015). "Gene expression databases have revealed that most cancers express both the gene encoding the insulin receptor and the gene encoding the IGF-1R." (PMID 24970814, 2014). "Both IGF-1R and INSR are found over-expressed in a variety of human cancer types and are associated with malignant tumor progression." (PMID 22879999, 2012). "Third, the overexpression of insulin receptor was demonstrated in numerous human cancers including HCC, and its overexpression was linked to tumor growth and cell survival." (PMID 21729319, 2011). "IRS2, encoding a kind of insulin receptor substrate that is commonly phosphorylated by the receptor tyrosine kinase, was reported to promote cell proliferation, invasion and sphere formation of cancer cells." (PMID 36092919, 2022). "NOS3, ACE, and INSR have high mutation frequencies in most cancer types." (PMID 35513851, 2022). "It’s reported that in hepatocytes and liver, PTPRE inactivates insulin receptor signaling, which might influence both risk and prognosis in many kinds of cancers." (PMID 33344226, 2020). "However, INSR signalling has so far been associated with adverse events that have limited the clinical success of anti-cancer strategies targeting IGF1R." (PMID 28192521, 2017). "The fact that these diseases are regarded as risk factors for cancer raises the question whether there is a direct connection between insulin and INSR and cancer." (PMID 24434591, 2014). "The complex relationship between altered INSR isoforms and cancer prognosis may help explain the challenges associated with targeting the IGF1R pathway in NSCLC and other cancers." (PMID 24571613, 2014). "The type of insulin receptor isoform present in malignant cells may play a role in the progression of cancer as well as in cancer risk." (PMID 23983688, 2013).
cancer (continued). "However, although other evidence supports that the inhibition of N-glycan biosynthesis enhances the effects of radiation in cancer cells, it remains unclear how changes in INSR/IGF1R-linked N-glycans could interfere with radiosensitivity in cancer cells." (PMID 28880250, 2017). "Insulin substantially promotes the growth of malignant cells that overexpress the insulin receptor (INSR), and insulin excess has been recognised as a cancer-promoting factor in patients." (PMID 42286874, 2026). "PPARƔ primarily inhibits the growth of cancer cells; emodin decreases IGFBP1; cladosporol, rosiglilazone and a bis-indole PPARƔ ligand induce p21; and thiazolidinediones (TZDs) decrease an insulin receptor via PPARƔ/Sp1 in cancer cell lines." (PMID 39858066, 2025). "They reported EGCG reduced tumor‐induced HIF‐1α by inhibiting cancer‐induced insulin receptor (IR) and IGF1R." (PMID 40755497, 2025). "Signaling through insulin like growth factor 1 receptor (IGF1R) and insulin receptor (IR) promotes cancer cell proliferation, survival, and treatment resistance in diverse malignancies." (PMID 39919036, 2025). "It is reported that miR-145 can play an important role in regulating tumor cell progression, migration, invasion, and apoptosis of some types of cancer by affecting c-Myc, Mucin-1, p70S6 kinase, and insulin receptor substrate." (PMID 39941094, 2025). "In search of prognostic biomarkers, we identified the insulin receptor (IR) to be overexpressed in cancer cells (CC-IR) and vasculature (VIR) of gastrointestinal cancer entities." (PMID 39775131, 2025). "INSR was found to be overexpressed in angiogenic vasculature of human tumors and the was correlated to shorter survival of cancer patient." (PMID 38874510, 2024). "Both INSR and FOXA1 were expressed at higher levels in OC cell lines than in FT190 cells, supporting a potential association with cancer." (PMID 39622796, 2024). "Activation of IRS proteins occurs in cancer cells when insulin binds to the Insulin Receptor (IR), leading to a chain of intricate signaling cascades." (PMID 38272982, 2024). "Multiple studies have demonstrated the implication of insulin receptor (IR) pathway in cancer development and progression." (PMID 39138146, 2024). "We previously proposed that this phosphorylation is associated with cell migration and cancer aggressiveness, distinguishing IGF-1R activity from that of insulin receptor, which lacks these tyrosines." (PMID 39608716, 2024). "The INSR plays significant roles in cancer progression, with overexpression in cancer cells leading to increased sensitivity to hyperinsulinemia." (PMID 38731097, 2024). "There is no debate that the increased expression of Neu-1 and MMP-9 has an impact on cancer progression through the modulation of inflammation, tumorigenesis, and insulin receptor signaling." (PMID 38534324, 2024). "KEGG enrichment analysis identified crucial nodes in the signaling pathways associated with cancer development, including VEGFA, INS, IGF1R, and INSR." (PMID 38305809, 2024). "The significance of INSR in cancer is further emphasized by their overexpression in various human malignancies, particularly IR-A, and their involvement in the formation of hybrid receptors with the IGF-IR." (PMID 38731097, 2024). "It was found that in cancer cells, their expression and signaling pathways are often dysregulated, and in many cancers, the INSR is overexpressed." (PMID 38397072, 2024). "The immune pathway mediated by pro-inflammatory cytokines such as IL-6 and TNF-α interferes with the biological effects of the insulin receptor downstream signaling and results in IR, which is also found to be closely involved in cancer development." (PMID 36969019, 2023). "In conclusion, more translational research is needed to reveal the underlying mechanisms between the genetic variation in IGF1R and INSR in the context of fasting and clinical response in cancer." (PMID 38136416, 2023).
cancer (continued). "The insulin receptor (INSR) gene has been studied less extensively in cancer, even though its protein can bind the same ligands as the IGF1R." (PMID 38136416, 2023). "BMS-754807 is an inhibitor of targeting insulin-like growth factor-1 receptor/insulin receptor (IGF-1R/IR) signaling pathway, which has been proven to be effective in suppressing tumor cell proliferation of xenograft tumor models of several cancer types." (PMID 35069736, 2022). "Cancer cells often overexpress the insulin receptor with a preferential expression of the IR-A isoform, which promotes growth and survival; knockdown in cancer cell lines results in smaller tumors and fewer metastases." (PMID 36079800, 2022). "In a similar way, MMP9 was shown to regulate the activity of nerve growth factor (NGF)-induced transmembrane receptor tyrosine kinase A (TrkA), EGFR/HER, and insulin receptor (IR) signaling in cancer cells." (PMID 35406619, 2022). "The IGF-1R shows a high degree of homology with the insulin receptor and hybrid IGF-1R/insulin receptor species have been reported in cancers." (PMID 36497428, 2022). "A previous study showed that following insulin stimulation in the insulin signaling pathway, SORBS1 mediated the functional transition of the insulin receptor from metabolism to cancer-related cell proliferation as well as migration." (PMID 35196185, 2022). "NOS3 was positively correlated and INSR was negatively correlated with the resistance of cancer to the majority of anti-cancer drugs." (PMID 35513851, 2022). "Increased levels of insulin and IGF-1 can would promote tumors growth and progression by binding to the overexpressed insulin receptor in many cancers." (PMID 35463353, 2022). "Since insulin receptor signaling also stimulates cell growth, hyperinsulinemia can potentially induce pathological disorders, including cancer and cardiovascular disease." (PMID 34202916, 2021). "Among the 20 most-enriched pathways, 8 (40%) relate to cancer, with the remainder relating to cell signaling and growth pathways, neuronal health, cardiovascular health and insulin receptor activity." (PMID 33593402, 2021). "It was observed that in tumor cells of certain cancers expression of insulin receptor, which promotes proliferation, is higher." (PMID 34489495, 2021). "Most experimental evidence gathered in recent years on the role of nuclear InsR/IGF1R was generated using cancer cell lines as well as freshly obtained tumors or archival specimens." (PMID 33918477, 2021). "The genes that harbored smoking-related methylation signals were enriched to fall in biological pathways related to cancer, cell signaling and growth pathways, neuronal health, cardiovascular health and insulin receptor activity." (PMID 33593402, 2021). "The staining intensities of InsR differed between the specimens, ranging from strong (2+) InsR expression in the cytoplasm (0–88%) and at the membrane (0–100%) of cancer cells, to weak (1+) cytoplasmic (0–100%) and membranous (0–70%) InsR expression." (PMID 34202040, 2021). "Linsitinib is an IGF‐1R and insulin receptor inhibitor currently under investigation for various types of cancer due to its ability to prevent tumor cell proliferation and induce tumor cell apoptosis." (PMID 34339582, 2021). "IGF not only binds to IGF-IR/InsR, but also directly binds to other receptors such as integrin, a family of adhesive receptors that promotes cancer stemness and cell survival to adapt to environmental and therapeutic stresses." (PMID 32493414, 2020). "Many of these pro-cancer, insulin-initiated signal transduction cascades rely on the insulin receptor (INSR) tyrosine kinase family." (PMID 33233470, 2020). "A peculiar example of the role of isoform switch by the insulin receptor signaling with direct possible implications on cancer malignant transition regards the regulation of EphB4 protein levels in cancer cells by the autocrine IGF-II/IR-A signaling axis." (PMID 33266015, 2020).